DLL3 (delta like canonical Notch ligand 3)
Diseases named in the same sentence as DLL3 in open-access papers (continued):
Sharing a sentence is not in itself a finding about the gene and the disease.
tumor (continued). "The expression of DLL3 was elevated in parts of tumor samples (red), with low expression in most normal tissues (white or blue)." (PMID 35382168, 2022). "In small-cell lung cancer (SCLC), DLL3 has been reported as a key factor in the promotion of the tumor growth, migration, and invasion of SCLC cells." (PMID 35628495, 2022). "DLL3 is an inhibitory Notch pathway ligand, which mediates cell-fate decisions and is tumor-suppressive or oncogenic depending on the cellular context." (PMID 36338696, 2022). "NIR-PIT targeting DLL3 with rovalpituzumab in an SCLC xenograft model has shown significant anti-tumor effects, suggesting that DLL3 is a promising target." (PMID 35884975, 2022). "Collectively, activated DLL3 can be oncogenic or tumor-suppressive, depending on the tumor type and cellular context." (PMID 35382168, 2022). "Between September 2016 and February 2019, 1293 patients were pre-screened for DLL3-positive tumor status; ~287 patients were ultimately screened for the study, and 200 patients were subsequently enrolled and received at least one dose of Rova-T." (PMID 34354225, 2021). "This demonstrates that it is worth assessing protein expression of biomarkers in general and here, especially of DLL3 in chemorelapsed samples, meaning in the latest tumor tissue." (PMID 34692726, 2021). "Delta-like protein 3 (DLL3) is a Notch ligand that is expressed in tumor-initiating cells and > 80% of SCLC and other high grade NECs (lung, ovarian, prostate, bladder, etc.), with minimal to no expression in normal tissues." (PMID 33916707, 2021). "In detail, 46.9% and 75% of SCLC and 48.8% and 53.7% of LCNEC specimens showed a high DLL3 expression by using H-score and percentage of positive tumor cells, respectively." (PMID 34568063, 2021). "From the four cases with several samples, three (75%) showed a concordant DLL3 expression between the samples (two DLL3-low, one DLL3-high), and the other one showed high-DLL3 expression in the primary tumor and low-DLL3 expression in the metastatic site." (PMID 34692726, 2021). "A Greek group widely studied CTCs with diverse phenotypes, and they observed a close relationship between changes in tumor burden and count of DLL3+, CD45− CTCs." (PMID 34066817, 2021). "In our study, among the low-grade NETs, 20%–25% of ACs and 5%–12% of TCs—assessed by H-score and percentage of positive tumor cells, respectively—have high DLL3 expression." (PMID 34568063, 2021). "Targeting the DLL3/Notch4 axis instead allowed to affect tumor-derived endothelial cells and neoplastic angiogenesis upregulated under doxorubicin therapy by reducing Notch4-driven transcription of VEGFR3." (PMID 34680255, 2021). "A greater DLL3 expression was also observed in tumors with visceral pleura infiltration, where 23/35 (65.7%) had ≥50% positive tumor cells and 18/35 (51.4%) had H-score ≥150." (PMID 34568063, 2021). "Regarding low-grade NETs, only 4.9% and 12.2% TCs and 19.5% and 24.4% ACs had high DLL3 expression considering H-score and percentage of positive tumor cells, respectively." (PMID 34568063, 2021). "DLL3 expression was considered positive if ≥ 1% of tumor cells showed cytoplasmic/membranous or dot-like immunostaining." (PMID 34513663, 2021). "Among the neoplasms with high DLL3 expression, 40/61 (65.6% using percentage value) and 31/45 (68.9% using H-score) presented a moderate-to-severe inflammatory infiltrate." (PMID 34568063, 2021). "Rova-T treatment decreased DLL3 expression in residual tumours, indicating that Rova-T kills DLL3-expressing TICs." (PMID 33257843, 2021). "We also demonstrated a high DLL3 expression in 48.8% of LCNECs by using H-score and 53.7% of LCNECs by using percentages of positive tumor cells, comparable with previous studies in LCNECs." (PMID 34568063, 2021). "In detail, 46.9% and 75% of SCLC specimens showed a high DLL3 expression by using H-score and percentage of positive tumor cells, respectively." (PMID 34568063, 2021).
tumor (continued). "In pooled patients with NEC/NET expressing a high level of DLL3 (≥50% DLL3-positive tumor cells), the ORR was 17% (6/35) and 34% (12/35) had a BOR (all PRs)." (PMID 34354225, 2021). "In those with NEC/NET expressing a low level of DLL3 (1–49% DLL3-positive tumor cells), the ORR was 9% (3/34) and the BOR rate was 15% (5/34) (all PRs)." (PMID 34354225, 2021). "The SCLC-A subtype is anticipated to respond to DLL3-targeted antibody drug conjugates due to the direct transcriptional interaction of DLL3 with ASCL1 in Notchinactive tumor cells." (PMID 33718595, 2021). "AMG 757, a half-life extended bi-specific T-cell engager, binds to DLL3 on tumor cells and CD3 on T cells, resulting in T cell-dependent killing of tumor cells." (PMID 34078406, 2021). "Nevertheless, overlap analysis identified well-established NE-associated genes such as DLL3 and its upstream regulator, achaete-scute complex-like 1 gene (ASCL1), as having distal ATAC-seq peaks and overlapping a tumor DMR in bulk tissue analysis." (PMID 32707835, 2020). "There is growing evidence supporting a tumor‐suppressor role for Notch‐1 signaling in neuroendocrine tumors, and DLL3 is considered to promote neuroendocrine tumorigenesis by inhibiting the Notch receptor pathway." (PMID 32691982, 2020). "In a study of 63 patients with SCLC, 52 (83%) patient tumor samples were found to be positive for DLL3 expression by immunohistochemistry (IHC), and 20 (32%) showed high expression of DLL3 (positive in at least 50% of cancer cells)." (PMID 31215500, 2019). "Epidermal growth factor-like domain multiple 7 (EGFL7), which modulates Notch2/DLL3 signaling, is involved in regulation of GHoma proliferation and invasiveness, and has been correlated with poor prognosis and tumor grade." (PMID 31508369, 2019). "The median overall survival was 5.6 months (95% CI, 4.9–6.8) in the overall enrolled population, while it was 6.7 in the DLL3-high (≥75% tumour cells positive for DLL3 by immunohistochemistry) patients." (PMID 31443481, 2019). "In order to identify the effect of DAPT on tumor progression by Notch2/DLL3 signaling pathway, Notch2/DLL pathways were detected by Western-blot." (PMID 31508369, 2019). "Recent studies have reported that DLL3 is also expressed in other tumor types of neuroendocrine origin, including melanoma, glioblastoma multiforme, small cell bladder cancer, metastatic castration-resistant prostate cancer, and neuroendocrine lung tumors." (PMID 31215500, 2019). "For this reason, the rapid tumor debulking seen with SC16LD6.5 was likely due to DLL3 expression on most tumor cells." (PMID 30984612, 2019). "Based on preclinical data, both BiTE® molecules and CAR T cells have the potential for direct cell killing of DLL3-positive SCLC tumor cells, even at low levels of DLL3 cell surface expression (< 1000 receptors per cell)." (PMID 31215500, 2019). "Rovalpituzumab tesirine (Rova-T) is an experimental antibody-drug conjugate targeting the protein DLL3 on tumor cells." (PMID 31781314, 2019). "DLL3 contributes to neuroendocrine tumorigenesis by inhibiting the Notch signaling pathway, whose role is to suppress tumor growth." (PMID 30053901, 2018). "In cases in which the tumor diameter was less than 5 cm, DLL3 expression was significantly lower (p = 0.0375) than in larger tumors." (PMID 29555949, 2018). "Dll1 and Dll3 seemed less expressed in the tumor epithelium, and Dll4, all Notch receptors, and Hes1 seemed upregulated." (PMID 28086833, 2017). "Integrative analyses identify DNA methylation-driven gene links based on location (H3K27ac, H3K27me3, promoters, gene bodies) pointing to mechanisms underlying dysregulation of genes involved in tumor lineage (ASCL1, AR) and therapeutic targets (PSMA, DLL3, STEAP1, B7-H3)." (PMID 40593552, 2025).
tumor (continued). "Further research is also needed to explore alternative therapeutic strategies for DLL3 negative tumours and to better understand the molecular mechanisms underlying DLL3 expression across the different types of NEN." (PMID 40153138, 2025). "NMF2 exhibits high tumor mutational burden (TMB) alongside elevated DLL3 expression, suggesting that it may respond to DLL3-targeted antibody-drug conjugates (ADCs) and immune checkpoint inhibitors." (PMID 40333678, 2025). "DLL3 is also present in circulating tumor cells and in blood samples from cancer patients." (PMID 40284515, 2025). "Clinical correlates reveal that elevated DLL3 expression associates with inferior outcomes in ES-SCLC and predicts enhanced response to DLL3-targeted therapies—patients with >75% DLL3+ tumor cells demonstrated a 38% objective response rate to Rova-T versus 11% in low expressers." (PMID 40496850, 2025). "Public data from the IMpower133 trial further validated the chemo‐resistant role of the MYC‐Notch‐non‐NE axis and highlighted the importance of the inhibitory Notch ligand, DLL3, in predicting response to chemo‐immunotherapy and promoting an immune‐supportive tumor phenotype." (PMID 39974662, 2025). "The dynamic DLL3 expression in response to treatment or tumor evolution leads to discrepancies between the initial biopsy and subsequent assessment, making it difficult to determine the most suitable candidates for DLL3-targeted interventions." (PMID 40284515, 2025). "This suggests DLL3 may identify more aggressive neoplasms with greater propensity for early metastasis." (PMID 41200177, 2025). "Bispecific antibodies can attach to immune effector cells, such as NK cells or T-cells, and then direct them to tumor cells by binding both to immune cell receptors (e.g., CD3 on T-cells) and tumor-associated antigens (e.g., CD19 on B-cells or DLL3 on neuroendocrine tumors)." (PMID 40277763, 2025). "Therefore, it is of the utmost importance to understand the biological context of DLL3 expression, including its interaction with other pathways and tumor microenvironmental factors, for effective patient classification and appropriate selection." (PMID 40284515, 2025). "This phase II trial utilized a rabbit antibody immunohistochemistry (IHC) assay to stratify study participants based on the percent expression of DLL3 found in tumor samples with at least 25% expression defined as DLL3-positive and at least 75% expression defined as DLL3-high." (PMID 40160238, 2025). "Synthesizing the early clinical data presented for TCEs targeting PSMA, STEAP1, and DLL3, a compelling picture emerges: T-cell engagers possess the intrinsic capability to elicit meaningful anti-tumor activity in heavily pretreated mCRPC patients, a population often refractory to standard therapies." (PMID 40507301, 2025). "Tarlatamab is a TCE that directs the patient’s T cells to cancer cells expressing DLL3, independent of major histocompatibility complex (MHC) class I. The Tarlatamab mechanism of action is based on its ability to simultaneously bind to T cells via CD3 and to tumor cells via DLL3." (PMID 40422520, 2025). "Furthermore, we investigated the distribution of DLL3 expression among different subtypes and grades of NEC and NET, and its association with the localization of the primary tumour." (PMID 40153138, 2025). "At last, expanding the range of tumor-specific targets beyond DLL3 could further broaden the scope of circRNA-based CAR-T applications to other malignancies." (PMID 40075480, 2025). "DLL3 overexpression on tumor cells is considered a potential target for NEPC treatment." (PMID 39372390, 2024). "DLL3 diffusely stains the cytoplasm of tumor cells in MTC with variable intensity." (PMID 38958823, 2024).
tumor (continued). "Gene expression analyses across these cell clusters confirmed that Ascl1/GFP, along with ASCL1 canonical NOTCH signaling target genes (Dll3, Notch1, Hes5) and the bHLH E-protein co-binding partners (Tcf4, Tcf12) were significantly elevated in Ascl1-OE tumor cells compared to control." (PMID 39609428, 2024). "Recently, tarlatamab, a bispecific TCE with a dual affinity for DLL3 on tumor cells and CD3 on T cells, showed impressive results in terms of antitumor activity, with durable objective responses and promising survival outcomes in patients with previously treated SCLC." (PMID 38791966, 2024). "The expression of DLL3 in tumor tissue was detected by Immunohistochemistry (IHC)." (PMID 38847733, 2024). "DLL3 expression was limited to NE tumor foci and was mutually exclusive of KRT8 expression." (PMID 39024561, 2024). "Her tumor strongly expressed DLL3 protein and had clinical response to tarlatamab therapy." (PMID 39619276, 2024). "DLL3 expression level in the tumor and NSE level in the serum may be useful biomarkers to predict the prognosis of SCLC." (PMID 38847733, 2024). "Tarlatamab (AMG 757) is the first DLL3-targeting bispecific T-cell engager therapy that activates a patient’s T cells to attack DLL3-expressing tumor cells, which is a bispecific T-cell engager molecule that binds both DLL3 and CD3, leading to T-cell-mediated tumor lysis." (PMID 39392394, 2024). "Additionally, a high trend towards significance was also found between DLL3 tumor expression (ρ = −0.154; p = 0.09) and NOTCH1 expression." (PMID 37893184, 2023). "Thus, lower tumor DLL3 expression will be found in the context of low stroma DLL3 expression and, consequently, more Notch activity will be found in those cases." (PMID 37893184, 2023). "Interestingly, upon multivariate analysis of OS, only DLL3 expression in tumor appeared to be statistically significant (p = 0.004)." (PMID 37893184, 2023). "In conclusion, our findings imply that DLL3 can be used as a stand-alone prognostic factor for many tumor types, and that the level of its expression will have a different prognostic impact for various tumor types." (PMID 37179118, 2023). "Because DLL3 is overexpressed in certain tumor cells, the current principle of therapeutic targeting of DLL3 is mainly to kill cancer cells by targeting DLL3 with antibody-coupled cytotoxic drugs or by specifically targeting cancer cells with high DLL3 expression through CD3-activated T cells." (PMID 37274780, 2023). "This suggests that these agents may exert an antitumor effect even in the case of low levels of DLL3 expression in some tumor cells—if a sufficient number of T cells are present." (PMID 37355629, 2023). "Additionally, several relationships between DLL3 expression levels and various subsets of tumor-infiltrating T cells were found." (PMID 37179118, 2023). "NK-92 cells that were transduced with a vector encoding the anti-DLL3 scFv domain, an NKG2D transmembrane domain, and a 2B4-CD3 domain exhibited specific antitumor activity against DLL3-positive cell lines and induced tumor regression in a pulmonary metastasis tumor model in immunodeficient mice." (PMID 37355629, 2023). "Thus, it seems that Rova-T exhibits encouraging single dose anti-tumor activity with controllable safety, especially in patients with high Dll3 expression." (PMID 37131214, 2023). "DLL3 expression is related to higher immune cell infiltrates in several tumor types and PDAC." (PMID 37893184, 2023). "Tarlatamab is a bispecific TCE with dual affinity for DLL3 on tumor cells and CD3 on T cells." (PMID 37355629, 2023). "Although these phenomena have not been documented with tarlatamab so far, monitoring of patients through the longitudinal analysis of immune cells and tumor DLL3 expression could provide important insights." (PMID 37355629, 2023).
tumor (continued). "HPN328 is a Tri-specific T Cell-Activating Construct (TriTAC) comprising three humanized antibody-derived binding domains: an N-terminal domain that binds DLL3 on tumor cells, a middle domain that binds to human serum albumin (for half-life extension), and a C-terminal domain that binds to CD3." (PMID 37355629, 2023). "In addition, initially, patients with high DLL3 expression (≥50% of tumor cells) showed better response rates and disease control than those with low DLL3 expression." (PMID 38001628, 2023). "Increasing evidence indicated that KRAS signaling could modulate the tumor microenvironment and promote tumor-related immune response, which was also found to be enriched in the low DLL3 expression group." (PMID 36338696, 2022). "In our series, DLL3 was expressed to a higher extent in cases with lower tumor stage." (PMID 35608806, 2022). "In addition, GSEA algorithm and gene sets of cancer hallmarks were utilized to further explore the role of DLL3 in tumor progression." (PMID 36338696, 2022). "Rova-T is an ADC comprised of a humanized anti-DLL3 mAb conjugated to a DNA-damaging pyrrolobenzodiazepine (PBD) dimer toxin that has been shown to induce sustained tumor regression across neural crest–derived malignancies including SCLC and LCNEC patient-derived xenograft (PDX) models." (PMID 36381237, 2022). "For example, in a preclinical model, the in vivo maximum efficacy dose of tarlatamab [a half-life extended (HLE) bispecific T-cell engager (BiTE) targeting DLL3] against patient-derived xenograft (PDX) tumor in a T cell-injected model using NOG mice was assessed to be 3 mg/kg14." (PMID 35853994, 2022). "The DLL3 expression was categorized as high (>50% positive tumor cells) or low (<50%)." (PMID 34568063, 2021). "We next investigated if the site of the biopsied recurrent tumor has an impact on DLL3 expression." (PMID 34692726, 2021). "Additional strategies targeting DLL3 in these difficult-to-treat tumor types warrant investigation." (PMID 34354225, 2021). "Higher DLL3 expression was more frequent in high-grade neoplasms." (PMID 34568063, 2021). "Three of the five cases with paired chemonaive primary and metastatic SCLC samples showed a concordant DLL3-high staining pattern, and in two cases, we observed a high-DLL3 expression in the primary tumor and a low expression in the metastatic site, assessed by TPS." (PMID 34692726, 2021). "For this patient, 97% of total tumor cells in his liver biopsy expressed DLL3 at 3+ intensity." (PMID 34385567, 2021). "Moreover, they used a different cutoff than we did with ≥25% positive tumor cells defined as positive DLL3 expression." (PMID 34692726, 2021). "Our results highlight the importance to investigate DLL3 in latest chemorelapsed SCLC tumor tissue." (PMID 34692726, 2021). "We next evaluated if there was a correlation between tumor site and DLL3 expression." (PMID 34692726, 2021). "In the low-grade neoplasm group, the DLL3 expression was higher in females (p < 0.001)." (PMID 34568063, 2021). "In addition, DLL3 is a novel target identified in tumor‐initiating cells isolated from SCLC and LCNEC patient‐derived xenografts." (PMID 32691982, 2020). "Thus, detecting the expression of DLL3 in tumour tissue will be helpful to guide therapy in Asian patients of SCLC." (PMID 32847588, 2020). "DLL3 is specifically expressed on the surface of SCLC tumor cells." (PMID 31215500, 2019). "In an exploratory analysis of 39 patients who provided tumor samples for analysis of DLL3 expression, 29 assessable patients had DLL3-high tumors (defined as expression in 50% or more tumor cells by IHC), and 10 (35%) of these patients had a confirmed objective response." (PMID 31215500, 2019). "In addition, the tumor responses seen after treatment with rovalpituzumab tesirine validate DLL3 as a target." (PMID 31215500, 2019).